HAVCR2 (hepatitis A virus cellular receptor 2)
Diseases named in the same sentence as HAVCR2 in open-access papers (continued):
Sharing a sentence is not in itself a finding about the gene and the disease.
HAVCR2 also shares sentences with these, for which no sentence is quoted: myeloma (34 papers); hematologic malignancies (29); rheumatoid arthritis (29); multiple sclerosis (27); renal cell carcinoma (27); chronic hepatitis B (25); myelodysplastic syndrome (25); prostate carcinoma (25); lymph node metastasis (18); diabetes (17); diffuse large B-cell lymphoma (17); infectious disease (17); multiple myeloma (16); abortion (15); tuberculosis (15); breast tumor (14); Cirrhosis (14); metastatic tumors (14); acute lymphoblastic leukemia (13); experimental autoimmune encephalomyelitis (13); metastatic melanoma (13); systemic lupus erythematosus (13); triple-negative breast carcinoma (12); Allergy (10); bladder urothelial carcinoma (10); chronic lymphocytic leukemia (10); preeclampsia (10); squamous cell carcinoma (10); bacterial infection (9); Hepatitis (9).
A further 297 diseases each share a sentence with HAVCR2 in 9 papers or fewer.